CD4 (CD4 molecule)
Diseases named in the same sentence as CD4 in open-access papers (continued):
Sharing a sentence is not in itself a finding about the gene and the disease.
tumor (continued). "Foxo1fl/flCD4Cre+ mice have the FOXO1 gene selectively deleted in CD4+ T cells, allowing us to investigate the T-cell-specific role of FOXO1 in tumor progression with or without a high Zn diet." (PMID 39247196, 2024). "By analyzing tumor-infiltrating immune cells, we found that LC treatment markedly increased the proportion of CD8+ T cells but did not alter the proportion of CD4+ regulatory T cells, CD11b+ myeloid cells and B cells in B16, MC38 and 4T1 tumor models." (PMID 38263463, 2024). "Our results confirmed that B4GALNT1 depletion significantly reduced tumor weight (p < 0.05), and the absence of B4GALNT1 led to a reduction in CD4 + T cells and CD163 + TAMs." (PMID 39616302, 2024). "At present, no report has been made on the relationship between CD4+ CTL and MPE; however, it has been acknowledged that CD4+ T cells can improve anti-tumour immunity." (PMID 38475858, 2024). "In the tumor microenvironment, CD4+ CD25+ Tregs have a negative impact on cytokine secretion and proliferation of CD4+ CD25- anti-tumor T cells." (PMID 38571964, 2024). "In the absence of tumor cells, ISB 2001 exhibited only minor T cell activation (as measured by CD25 upregulation on CD8+ and CD4+ T cells) compared to the CD3 × CD38 TCE control." (PMID 39261676, 2024). "All variables were analyzed by LASSO regression, and when the λ coefficient decreased to the optimum as the number of variables increased, four variables with non-zero coefficients were selected: Tumor area CD3+, PDL1+, CD3+PD-L1+, CD4+PD-1+." (PMID 38726002, 2024). "CD4+ T cells, unlike CD8+ T cells that can directly kill tumor cells, function mainly by releasing different cytokines to regulate other immune cells and play an equally important role as CD8+ T cells." (PMID 39703499, 2024). "When cell suspension from MC38 tumor tissue was incubated with these fusion proteins in vitro, αPD1-mIL12mut2 preferentially bound to CD8+T cells rather than CD4+T cells or NK cells." (PMID 38830882, 2024). "Collectively, these results confirmed that the deletion of Panx1 did not affect the infiltration of CD4+ and CD8+ T lymphocytes in the tumors, although the cytotoxic effect seemed to be insufficient to prevent the tumor progression in BPC‐Panx1−/− mice." (PMID 38327091, 2024). "Therefore, differentiating naïve CD4+ T cells into Th1 without blocking the B7-CTLA-4 interaction may potentially lead to a reduction in the clinically observed side effects while still maintaining strong anti-tumor efficacy." (PMID 39106430, 2024). "Upon examining the tumor-immune infiltrate from B16 tumors after 10 days of treatments, we observed an increase in CD8+ and CD4+ Teffs in the combination treatment group that was not detectable in either monotherapy treatment group." (PMID 39225102, 2024). "Decreased IFN-γ expression was observed in tumor-infiltrating CD8+ T cells from the Id2fl/flCd4-Cre+ mice compared to the Id2fl/flCd4-Cre− mice, while no such difference was observed in CD4+ T cells." (PMID 38287103, 2024). "In CNRT, tumor inhibition was also attenuated after depletion of CD8+ T cells, but the depletion of CD4+ T and NK cells did not significantly affect radiation-induced tumor suppression." (PMID 39736508, 2024). "The antitumour effects in Tigit−/− mice were abolished when depletion of CD8+ T cells, rather than NK cells, CD4+ T cells, or Tregs, indicating that CD8+ T cells are essential for inhibiting tumour growth when TIGIT is depleted." (PMID 38279870, 2024). "GSDMA expression showed a significant negative correlation with the tumor purity of LIHC (p < 0.05) and a significant positive correlation with the degree of infiltration of B cells, CD8+ T cells, CD4+ T cells, macrophages, neutrophils, and dendritic cells." (PMID 38434972, 2024). "The absence of CD4+ T cells can impede the eradication of tumor cells, and research has demonstrated that inactivation of the oncogene MYC can recruit CD4+ T cells to the tumor site and induce sustained regression of tumors." (PMID 38426090, 2024).
tumor (continued). "Throughout the immune editing process, CD8+ and CD4+ T cells recognized non-self peptide epitopes that were displayed by MHCI and MHCII molecules expressed on tumor cells, and contributed to the suppression of tumor growth." (PMID 38713284, 2024). "The five remaining models contained immune cells (CD4+ and CD8+ T cells, and macrophages), non-immune cells (fibroblasts), and tumor cells." (PMID 38605943, 2024). "Compared with the non-responded tumors, it seemed that the responded tumor was infiltrated with more CD8+ T cells, less CD4+ T cells, less CD19+ B cells, and less CD163+ M2 macrophages." (PMID 38637495, 2024). "CCR8 is highly expressed in the tumor microenvironment, especially in Tregs, whereas NK cells, CD8 + T cells, myeloid cells, and most CD4 + T cells do not express CCR8." (PMID 38915099, 2024). "Surprisingly, the SEP without tumor group was highly abundant in T lymphocytes primarily composed of natural killer cells, and effector CD8+ and CD4+ T cells." (PMID 39191486, 2024). "We examined if CCL21-induced pDCs suppress anti-tumor immunity via Tregs; however, using co-culture of CCL21-induced pDCs with naïve CD4 T cells, neither Treg lineage induction nor Treg proliferation was observed." (PMID 39456552, 2024). "In a mouse model of EGFR-mutated lung adenocarcinoma, which has a non-inflammatory immunosuppressive tumor microenvironment, EGFR signaling recruits CD4+ regulatory T cells and CD8+ T cell infiltration by activating JNK/cJun and inhibiting IRF1." (PMID 38762484, 2024). "In tumour tissues, the abundance of GzmB, perforin, TNF-α, and IFN-γ is significantly decreased in CD4+, CD8+ T cells, and NK cells compared to non-tumour tissues." (PMID 38893071, 2024). "Interestingly, we observed that two CD8 GZMB+ subsets, one CD4 GZMB+ subset and one γδ T GZMB+ subset was predominantly derived from individual patients and were detected at both time points, suggesting that GZMB+ cytotoxic T cells may perform anti-tumor specific immune response in the TME." (PMID 39505839, 2024). "Tumor cells typically have an NK-cell phenotype, expressing CD2, CD3ε, and CD56, with no expression of surface CD3, CD4, or CD5." (PMID 38611591, 2024). "When tumors did develop in these mice, regardless of CD4 depletion, topical SQV decreased the tumor growth rate over time." (PMID 39339897, 2024). "Concurrently, there was a shift in the proportions of CD4+ T cell subsets in the spleen and an increase in the frequency of CD8 T cells in the non-irradiated tumor draining lymph nodes." (PMID 38646546, 2024). "Through this enhancement, the endogenous immune system was primed, where robust CD4+ and CD8+ T-cell responses were gained against non-CAR tumor antigen, greatly increasing the tumor infiltration." (PMID 38685033, 2024). "COL4A2 did not correlate with tumor purity and B-cell infiltration but positively correlated with CD8 + T-cell, dendritic cell, macrophage, neutrophil, and CD4 + T-cell infiltration." (PMID 38907304, 2024). "Together, our data suggest that NF1, TSC1, or TβRII inactivation resulted in a tumor cell non-autonomous immune suppressive microenvironment that is potentially mediated by LAG3+ CD8 T and CD4 T cells." (PMID 38997291, 2024). "ZFP36 KO did not alter antigen-induced CD25 and CD69 expression in CD4 or CD8 mesoCAR-T cells, nor did it change the percentage of CD25+ CD69+ cells without tumor cells." (PMID 38326511, 2024). "Strikingly, in inflammation-induced AOM/DSS tumors, we found increased infiltration of CD4+ T cells and FOXP3+ Tregs, but not of CD8+ cells or F4/80+ macrophages into FibΔZeb1 tumors, indicating modulation of adaptive anti-tumor immunity." (PMID 38937629, 2024). "Because cDC1s primarily activate CD8+ T cells 17-19, while cDC2s are required for initial priming of CD4 T cells 17, these results indicate that we should not expect a biasing toward CD4+ or CD8+ T cell activation due to uneven cDC tumor antigen acquisition." (PMID 38389838, 2024).
tumor (continued). "Analysis of tumor‐infiltrating lymphocytes (TILs) revealed increased CD8+ TILs in the PS‐treated group, whereas CD4+ and NK1.1+ TILs showed no significant changes." (PMID 38900071, 2024). "None of the 17 elicited tumor control in vivo, even as 7 of 17 elicited specific CD8 and/or CD4 responses." (PMID 38426497, 2024). "Cell type analysis showed that PBMCs of SEP without tumor group were mainly T cells (CD8+ and CD4+) and NK cells." (PMID 39484369, 2024). "Together, these data indicated that anti-TIGIT antibodies can engage activating Fc receptors to activate tumour macrophages, positively modulate tumour CD8+ and CD4+ T cells, and inflame circulating non-classical monocytes." (PMID 38418879, 2024). "As the results showed, the proportion of CD4 + T and CD8 + T cells did not change in lymph nodes, while the proportion of CD8 + T cells within the tumor both increased in the PEPTIDE and PEPTIDE + anti-PD1 group." (PMID 38630135, 2024). "Next, flowcytometric analysis revealed a significant increase in tumor-infiltrating lymphocytes (TILs) in non-irradiated tumors in the RTRT-treated group, such as CD4+ and CD8+ T cells." (PMID 39736508, 2024). "While in our YTN16 peritoneal dissemination model, the combination of anti-CD4 mAb with dual ICI effectively depleted Tregs, leading to a substantial influx of CD8 + T cells into the tumor, the tumor still showed no improvement." (PMID 38805119, 2024). "Further analysis showed that there were more CD3 and CD8 T cells but not CD4 T cells, in OVCAR3 tumours from mice treated with nfP2X7 CAR‐T cells when compared with UT CD3 T cells." (PMID 38800555, 2024). "Moreover, another study showed that CD4+ T cells lacking Atg3 or Atg5 can increase IL-9 expression and autophagy inhibition enhanced T helper 9 cell anticancer effects in vivo, and mice with T cell-specific deletion of Atg5 showed decreased tumor outgrowth in an IL-9-dependent manner." (PMID 38627815, 2024). "In the mIHC analysis, compared to non-responded tumor, it seemed that responded tumor was infiltrated with more CD8+ T cells, and less CD4+ T cells, CD19+ B cells and CD163+ M2 macrophages." (PMID 38637495, 2024). "Unlike CD4 and CD8 T cells, which can follow various tumor infiltrating profiles, B TILs are rarely found on their own." (PMID 39086481, 2024). "Analysis of the frequency of PD-1+ lymphocytes revealed a higher abundance of both CD8+ and CD4+ T cells in SKOV-3 Luc tumor-bearing Hu-mice compared to mice without detectable BLI and tumor growth." (PMID 38789484, 2024). "We found that vaccination with the CD8-restricted OVA peptide, led to infiltration of endogenous CD8 T cells, but not CD4 T cells or Tregs, in both B16F10 and KPC3-TRP1 tumor models, independent of CD3 bsAb administration." (PMID 38167722, 2024). "In line with findings in Rag1−/− mice, elimination of CD8+ T cells did not affect tumor response to DCP-IL-12/FLT3L and, remarkably, simultaneous elimination of CD8+ T cells, CD4+ T cells and NK1.1+ NK cells only moderately rescued tumor growth." (PMID 37996514, 2024). "Mammary epithelial cells lacking USP18 induce the recruitment of Th1-subtype CD4 T cells by increasing IFN-γ-mediated Cxcl10 secretion, thus forming a tumor-suppressive microenvironment." (PMID 39334957, 2024). "The γδT cells, characterized by the expression of γ and δ chains and predominantly lacking CD4 and CD8 markers, exhibit non-MHC-restricted cytotoxicity against tumor cells." (PMID 38887597, 2024). "Quantitative analyses further confirmed these observations, showing significantly greater densities of CD4+PD-1+ and CD8+PD-1+ cells in the Response group compared to the Non-response group within the tumor region." (PMID 38726002, 2024). "CD8+T cells are a key part of anti-tumour immunity, however, not only CD8+T cells play a key role in anti-tumour immunity, the anti-cancer effect of CD4+T cells can not be ignored." (PMID 39816386, 2024).
tumor (continued). "However, like CD3 monitoring, because CD4 is expressed on both Tregs and CD4 helper T cells, its utility in stratifying responders and non-responders may be limited due to a lack of specificity for anti-tumor T cells." (PMID 39104861, 2024). "High detection of PD-1 in immune cells infiltrating tumor epithelial islands correlated with the presence of high expression of CD8+ CTL (p=0.003), but not with CD4+ TH and CD68+ cells (p=0.604 and p=0.907, respectively)." (PMID 39035008, 2024). "Even if other immune cells such as NK-cells or CD4+ cells can also produce IFNγ, a depletion of these cell types, in contrast to CD8+ T-cell depletion, did not lead to a reversal of the tumour growth reduction." (PMID 38271469, 2024). "Summarizing, encapsulating metastases display a greater infiltration, although with discrete values, of cytotoxic cells on tumor cells than nonencapsulating metastases, a fact that is confirmed by a higher intraepithelial CD8‐to‐stromal CD4 ratio." (PMID 39563958, 2024). "Although the average CD4/CD8 ratio was slightly higher in MOC1-HPV K1 and MOC1-HPV K3 tumors, the differences between the three tumor models were not statistically significant." (PMID 37296466, 2023). "We found that the risk of death was three-fold higher among non-operated patients with low tumor cell MSLN expression, high PD-L1 levels, and low infiltration of T cells CD4+ in the TME." (PMID 37901248, 2023). "Tumor type did not influence the cell counts of CD45+, CD3+ T, CD3+CD4+ Th, CD3+CD8+ CTL, CD19+ B and CD16+CD56+ NK (P > 0.05)." (PMID 38102684, 2023). "In contrast, PancVAX2, which contains both CD4 and CD8 neoepitopes, provides a significant reduction in tumor growth and a long-term survival benefit without concomitant checkpoint modulation." (PMID 38063199, 2023). "Dimensionality reduction, visualization using uniform manifold approximation and projection (UMAP) and cell type annotation using SingleR showed a clear separation between the monocyte–macrophage clusters derived from CD4 ACT-treated and non-treated tumours." (PMID 37316667, 2023). "With the exception of a few immune infiltration cells between each other that showed negative correlation, such as between CD4+ T cells and CD8+ T cells, most tumor immune cells exhibited mutual promotion." (PMID 37000317, 2023). "We observed that patients with high levels of sTILs, CD4 + T, and CD8 + T cells are more frequently diagnosed at earlier clinical stages (I/II), with smaller tumor sizes and no lymph node involvement." (PMID 38044375, 2023). "Our finding that IL-2 restriction is the major mechanism of Treg-mediated regulation of self- and tumor-reactive CD8+ T cells does not exclude the involvement of additional mechanisms regulating other immune cell types, such as conventional CD4+ T cells." (PMID 36705564, 2023). "In the small two-tumor model (~ 100 mm3), depleting CD4 + and CD8 + T cells did not prevent CpG + OX40 from significantly inhibiting local tumor progression." (PMID 37016127, 2023). "Similar to observations in CD4+ TILs, a large proportion of CD8+ TILs in early-stage tumours (D7) were double-negative for both transcription factors (T-bet-Eomes-, 66% of total CD8+ TILs)." (PMID 37153625, 2023). "The CD4+ and CD8+ T cell depleted vaccinated/challenged birds were protected with no clinical signs or tumor development at termination (Rows 3 and 4, respectively)." (PMID 36992357, 2023). "The total cell numbers of effector CD4+, CD8+ T cells, and NK cells, as well as immunosuppressive Tregs, were not substantially changed in the chemotherapy-treated tumor-free mice." (PMID 36976637, 2023). "In the untreated index tumor, all RFA treatment groups (RFA-lip-GM-CSF, RFA-BL, RFA alone) demonstrated an equivalent shift towards CD8+ cells, as compared to no-shift in CD4/CD8 ratios for all non-RFA arms (lip-GM-CSF, fr-GM-CSF, and sham) (p<0.05)." (PMID 37883367, 2023).
tumor (continued). "The results indicate that CD8+ T cells, but not CD4+ T cells or IFN-γ, have the most profound effect on the prevention of regrowth of the B16F10 tumor." (PMID 38019919, 2023). "Consistent with previous evidence of a cold tumor microenvironment in PanNETs, our findings showed that human PanNET liver metastases had low numbers of both CD8+ and CD4+ T cells (data not shown)." (PMID 37843277, 2023). "Preclinical trials from the second approach revealed that rigosertib, but not anti-PD-1, increased CD8/CD4 T cell ratios in spleen and blood and inhibited PDX tumor growth." (PMID 37509357, 2023). "To dissect the influence of the tumor on the dynamics of CD431B11+CD8+ and CD431B11+CD4+ T cells, we treated non-tumor-bearing mice (mock challenged) with anti-OX40/CpG, anti-PD-L1, or PDOX." (PMID 36796366, 2023). "Analysis of CD4 and FoxP3 staining showed that neither docetaxel monotherapy nor docetaxel + NHS-IL-12 combination therapy altered Treg frequency in the tumor." (PMID 37166485, 2023). "This suggests that in the presence of tumor-derived antigens, CD40 signaling in cDC1s is critical not only for CD8+ T cell initiation but also for early activation of naïve CD4+ T cells." (PMID 37183207, 2023). "When studying paired tumor biopsies from patients with a high versus low MNTR, however, we did not observe differences in densities of CD4+ T-cells, CD8+ T-cells or CD66b+ neutrophils, nor differences in distances among these cells." (PMID 35976415, 2023). "Following an ex vivo 6-h co-culture of lung and spleen cells with viable 4T1 tumor cells, we observed a significantly (p ≤ 0.05) higher proportion of both CD8+ CD69+ CD44hi and CD4+ CD69+ CD44hi T cells from the lungs but not spleen." (PMID 36839766, 2023). "The resulting efficient in vivo T‐subset depletion (Fig EV2B), showed that the main Lenti‐HPV‐07‐induced effectors involved in tumor elimination were CD8+ T cells and that CD4+ T cells made no sizeable contribution." (PMID 37675835, 2023). "PD-1 expression was markedly upregulated in CD4, CD8, and regulatory T (Treg) cells, but not in B cells, from tumor-bearing mice, compared to those from tumor-free mice." (PMID 37147330, 2023). "IHC results demonstrated that CD3+ and CD8+ T cells were evidently increased in tumor periphery and inner areas of RT/TMZ/PL group compared to all other groups, while CD4+ T cells were slightly increased and Treg cells were not altered." (PMID 37161450, 2023). "As expected, we found that the majority of LAG-3 was expressed by tumor-infiltrating, but not circulating, CD8 memory T cells, with lower, but detectable, levels of LAG-3 on tumor-infiltrating CD4 T-helper cells and Tregs." (PMID 37795090, 2023). "The results from TIMER demonstrated a positive correlation between PDIA3 and tumor-infiltrating CD8 T cells and macrophages, and a negative correlation with tumor-infiltrating CD4 T cells." (PMID 37909009, 2023). "Taken together, these results confirm that most of the LAG-3 expression in patients with solid tumors is found on tumor infiltrating, but not circulating, CD8 and CD4 memory T cells." (PMID 37795090, 2023). "Anti-tumor responses were lost following CD8+, but not CD4+, T-cell depletion and enhanced by PD1 blockade, confirming that tumor cell-derived Type I IFNs lead to a tumoricidal adaptive immune response." (PMID 36918588, 2023). "Burack and others demonstrated that CD4+ Th cells are essential tumor microenvironment elements to the PDX models, and depletion of CD4+ Th cells but not CD8+ T cells prevented PDX engraftment." (PMID 37297008, 2023). "In contrast, KGs expression was not significantly correlated with tumor purity or infiltrating levels of CD8+ T cells, CD4+ T cells or neutrophils in CRC." (PMID 36991484, 2023).